UBA5 (ubiquitin like modifier activating enzyme 5)
Description:
E1-like enzyme which specifically catalyzes the first step in ufmylation. Activates UFM1 by first adenylating its C-terminal glycine residue with ATP, and thereafter linking this residue to the side chain of a cysteine residue in E1, yielding a UFM1-E1 thioester and free AMP. Activates UFM1 via a trans-binding mechanism, in which UFM1 interacts with distinct sites in both subunits of the UBA5 homodimer. Trans-binding also promotes stabilization of the UBA5 homodimer, and enhances ATP-binding. Transfer of UFM1 from UBA5 to the E2-like enzyme UFC1 also takes place using a trans mechanism. Ufmylation plays a key role in various processes, such as ribosome recycling, response to DNA damage, interferon response or reticulophagy (also called ER-phagy). Ufmylation is essential for erythroid differentiation of both megakaryocytes and erythrocytes (By similarity).
Synonyms: UBE1DC1; FLJ23251; DEE44; EIEE44; SCAR24; THIFP1
Tractability: Small molecule: a structure with a bound ligand is known; it has a binding pocket of medium quality. PROTAC: ubiquitination databases record sites on it; its protein half-life has been measured.
Target class: Enzyme
Gene: Protein-coding gene on chromosome 3 (132,654,446 to 132,679,794, forward strand). Ensembl gene ENSG00000081307.
Subcellular location: Cytoplasm; Nucleus; Endoplasmic reticulum membrane; Golgi apparatus
Subcellular location (Human Protein Atlas): Cytosol; Vesicles
Pathways (Reactome):
Disease: Dengue Virus Attachment and Entry
Immune System: Antigen processing: Ubiquitination & Proteasome degradation
Gene Ontology:
Molecular function: protein binding; protein homodimerization activity; UFM1 activating enzyme activity; zinc ion binding; ubiquitin-like modifier activating enzyme activity
Biological process: neuromuscular process; protein K69-linked ufmylation; protein ufmylation; regulation of intracellular estrogen receptor signaling pathway; response to endoplasmic reticulum stress; reticulophagy; erythrocyte differentiation; megakaryocyte differentiation; regulation of type II interferon production
Cellular component: cytoplasm; cytosol; endoplasmic reticulum membrane; Golgi apparatus; nucleus
Genetic constraint (gnomAD): Loss-of-function variants: 20 observed, 34.67 expected, observed/expected ratio (o/e) 0.58, 90% interval 0.41 to 0.84. The upper end of that interval is the gene's LOEUF score, 0.84, which puts it in group 3 of 6, group 1 being the genes least tolerant of losing a copy. Missense variants: 314 observed, 383.26 expected, observed/expected ratio (o/e) 0.82, 90% interval 0.75 to 0.9. Synonymous variants: 115 observed, 126.96 expected, observed/expected ratio (o/e) 0.91, 90% interval 0.78 to 1.06.
Gene-disease validity (ClinGen):
ClinGen rates the evidence that UBA5 causes each of these diseases.
genetic developmental and epileptic encephalopathy (autosomal recessive): Definitive. A complex neurodevelopmental disorder characterized by a range of developmental delays and epileptic encephalopathy phenotypes.
Homologues: Orthologues: chimpanzee UBA5 (99% identical), macaque UBA5 (98% identical), dog UBA5 (96% identical), pig UBA5 (95% identical), guinea pig UBA5 (92% identical), rat Uba5 (88% identical), mouse Uba5 (88% identical), rabbit UBA5 (88% identical), tropical clawed frog uba5 (80% identical), zebrafish uba5 (79% identical), Drosophila melanogaster Uba5 (65% identical), Caenorhabditis elegans uba-5 (60% identical). Paralogues in human: MOCS3 (25% identical), UBA1 (19% identical), UBA6 (17% identical), UBA7 (17% identical), ATG7 (16% identical), UBA2 (14% identical), UBA3 (12% identical), NAE1 (6% identical), SAE1 (6% identical).
Diseases named in the same sentence as UBA5 in open-access papers:
UBA5 is named in the same sentence as 43 diseases in open-access papers, as found by Europe PMC text mining. Sharing a sentence is not in itself a finding about the gene and the disease. The quoted sentences say what the papers report.
anemia (7 papers, 2014 to 2023). A reduction in the number of red blood cells, the amount of hemoglobin, and/or the volume of packed red blood cells. "A previous study revealed that Uba5-deficient mice died in utero owing to severe anemia combined with the defective differentiation of both megakaryocytes and erythrocytes." (PMID 35884562, 2022). "The anemia phenotype of the Uba5-deficient mouse embryos can be rescued by transgenic expression of Uba5 in the erythroid lineage, together with prolonged survival, although Uba5 is dispensable for the erythropoietin production." (PMID 27212118, 2016). "Significantly, UBA5-deficient mice die in utero due to severe anemia associated with defective differentiation of both megakaryocytes and erythrocytes, although UBA5 is dispensable for the production of erythropoietin." (PMID 25852645, 2015). "Further study illustrated that the loss of UBA5 is associated with the defective differentiation of both megakaryocytes and erythrocytes, while the transgenic expression of UBA5 in the erythroid lineage rescued the Uba5-deficient embryos from anemia and prolonged their survival." (PMID 35884562, 2022). "Moreover, transgenic expression of UBA5 in the erythroid lineage rescues the UBA5-deficient embryos from anemia and prolongs their survival, revealing that the UFM1-conjugating system has an essential role in erythroid differentiation." (PMID 25852645, 2015). "The resulting anemia is considered to be the main cause of death in Uba5−/−-deficient mice embryos." (PMID 24921187, 2014). "An analysis of UBA5−/− mouse embryos at different developmental stages revealed a marked fetal anemia phenotype compared with UBA5+/+ mouse embryos that was rescued by transgenic expression of UBA5 in the erythroid lineage." (PMID 37947621, 2023). "UBA5 knockout is embryonic lethal in mice because of severe anemia resulting from defective hematopoiesis, and loss of function of this gene is also embryonic lethal in fruit flies." (PMID 33811063, 2021). "Significantly, Uba5 knockout mice die in utero due to severe anemia resulting from defective development in the megakaryocyte and erythroid progenitors." (PMID 27212118, 2016). "For instance, Uba5 knockout mice exhibited severe anemia, followed by death in utero." (PMID 35884562, 2022). "Although a cell-specific rescue of Uba5 stopped anemia, prenatal death could not be prevented, indicating the additional essential roles of the Ufm1 system." (PMID 24921187, 2014).
developmental delay (7 papers, 2016 to 2025). "In 2016, we reported for the first time that compound heterozygous variants of UBA5 lead to neurodevelopmental disorders characterized by cerebellar atrophy and developmental delays." (PMID 39085203, 2024). "Variants in UBA5 have been reported to cause neurological disease with impaired motor function, developmental delay, intellectual disability and brain pathology as recurrent clinical manifestations." (PMID 38046095, 2023). "Moreover, mutations in UFM1 and UFC1 were shown to cause neurologic disease with global developmental delay, progressive microcephaly, short stature and refractory epilepsy, a phenotype highly reminiscent of that observed in individuals with UBA5-related epileptic encephalopathy." (PMID 38046095, 2023). "A 0.4-Mb heterozygous loss in 3q22.1, which includes UBA5 and NPHP3, was previously detected in a patient with global developmental delays, impaired hearing, muscular hyptonia, and seizures." (PMID 26872069, 2016). "Moreover, copy number variations in UBA5 or ubiquitin-fold modifier 1 gene (UFM1) were documented with the phenotypes of global developmental delays and gait disturbances in the ClinVar database." (PMID 26872069, 2016). "Variants in the UBA5 gene are associated with developmental and epileptic encephalopathy 44 (DEE44), an autosomal recessive disorder characterized by early-onset encephalopathy, movement abnormalities, global developmental delay, intellectual disability, and seizures." (PMID 37502976, 2023).
Encephalopathy (7 papers, 2019 to 2025). Encephalopathy is a term that means brain disease, damage, or malfunction. "Whole exome sequencing (WES) unveiled rare biallelic mutations in UBA5 among five children from four different families, all of whom suffered from early-onset encephalopathy accompanied by microcephaly." (PMID 39757643, 2025). "Allelic strengths of encephalopathy-associated UBA5 variants correlate between in vivo and in vitro assays." (PMID 39590469, 2024). "Biallelic mutations in the UBA5 (ubiquitin-activating enzyme of UFM1) gene were recently seen to cause SCAR24 and early onset encephalopathy with intellectual deficiency, microcephaly, movement disorders, and epilepsy." (PMID 33917666, 2021). "Of note, variants in UBA5 and UFM1 in the same ufmylation pathway have also been described in patients with early-onset encephalopathy." (PMID 30552426, 2019). "Thus, it is possible that the explanation for growth failure in UBA5-related encephalopathy lies in a yet unidentified target of UFMylation." (PMID 33811063, 2021).
epilepsy (6 papers, 2020 to 2025). A brain disorder characterized by episodes of abnormally increased neuronal discharge resulting in transient episodes of sensory or motor neurological dysfunction, or psychic dysfunction. "Individuals with UBA5 variants can develop severe irritability, stagnation of development and epilepsy." (PMID 37139330, 2023). "In the same way, several DEEs caused by mutations in CDKL5, DNM1, KCNT1, SCN1A, SCN2A, SCN8A, and UBA5 genes, which present severe pharmaco-resistant epilepsy, are increasingly becoming targets for RNA molecules that aim to restore neuronal excitability and network function." (PMID 41244709, 2025).
microcephaly (5 papers, 2018 to 2025). A congenital or acquired developmental disorder in which the circumference of the head is smaller than normal for the person's age and sex. "Subsequently, a series of biallelic variants of UBA5 were discovered in patients, causing severe infantile-onset epileptic encephalopathy primarily characterized by microcephaly." (PMID 39085203, 2024). "Using exome sequencing, two groups found two biallelic mutations in UBA5 (A371T and a loss-of-function nonsense mutation) that led to postnatal microcephaly, epilepsy, and spasticity in severe epileptic syndrome patients." (PMID 37947621, 2023). "The recent finding that biallelic mutations in UBA5 (the E1-like enzyme for ufmylation) cause severe early-onset encephalopathy with progressive microcephaly implicates ufmylation in human brain development." (PMID 29868776, 2018). "Mutations in UFM1, as well as in its specific E1 enzyme UBA5 and E2 enzyme UFC1, have been genetically linked to microcephaly." (PMID 39085203, 2024). "Genetic studies have revealed that variants of the human UBA5, UFC1, and UFM1 genes are associated with a number of neurodevelopmental diseases, including infantile-onset encephalopathy, autosomal recessive cerebellar ataxia, and microcephaly." (PMID 37947621, 2023). "Additionally, in a patient with acquired microcephaly, motor disorders, and neurodevelopmental delay, a 597 kb deletion resulting in complete UBA5 deletion on chromosome 3q22.1 was detected, alongside a hemizygous missense mutation c.1166A G (p.Asp389Gly) on another chromosome." (PMID 39757643, 2025). "The clinical phenotype of previously reported patients with UBA5 and UFM1 mutations are similar to our UFM1 and UFC1 patients, particularly regarding failure to thrive, short stature, microcephaly, GDD, seizures, basal ganglia abnormality, delayed CNS myelination, and cerebellar hypoplasia." (PMID 29868776, 2018). "Apart from UBA5, homozygous variation of UFM1 (c.241C > T (p: Arg81Cys) and UFC1 (c.317C > T (p: Thr106Ile), c.68G > A (p: Arg23Gln)) were also identified in multiple children with progressive microcephaly." (PMID 39757643, 2025).
breast carcinoma (4 papers, 2016 to 2023). "In a study of colon cancer, depleting UfSP2 significantly promoted the growth of tumor cells, while UBA5 can be upregulated in breast cancer and associated with poor prognosis." (PMID 37947621, 2023). "Meanwhile, the E1 activating enzyme UBA5 was found to be upregulated in breast cancer and associated with poor prognosis." (PMID 35884562, 2022). "However, the physiological functions and associated underlying molecular mechanisms of UBA5 in breast cancer remain to be explored." (PMID 34572561, 2021). "Taken together, high expression of UBA5 was observed in breast cancer, and UBA5 expression may be a risk factor for breast cancer patients." (PMID 34572561, 2021). "Our results showed that UBA5 was upregulated in breast cancer and it expression was correlated with worse clinical outcomes." (PMID 34572561, 2021). "In this study, we reported that usenamine A exhibits UBA5 inhibitory activity in breast cancer cells." (PMID 34572561, 2021). "According to our research, UBA5 was overexpressed in a broad spectrum of tumors, including breast cancer." (PMID 34572561, 2021). "A previous study showed that the knockdown of UBA5 effectively prevents the growth of breast cancer." (PMID 34572561, 2021). "Further survival analysis indicated that high expression levels of UBA5 were related to poor prognosis in breast cancer patients." (PMID 34572561, 2021). "Knockdown of UBA5 has been shown to inhibit breast cancer cell growth, implying the low activity of this ubiquitination system is beneficial for patient survival." (PMID 27690302, 2016). "We also discovered that UBA5 was upregulated in breast cancer." (PMID 34572561, 2021). "Moreover, UBA5 was highly expressed in breast cancer than in other cancers, a result that was also confirmed by the UALCAN database." (PMID 34572561, 2021). "According to the bioinformatics analysis results, UBA5 was upregulated in breast cancer." (PMID 34572561, 2021). "We further explored whether usenamine A is able to activate ER stress and induce autophagy, considering it dose-dependently inhibited UBA5 expression in breast cancer cells." (PMID 34572561, 2021). "However, the inhibition of LC3B induced by UBA5 could be reversed by usenamine A. Thus, usenamine A is a promising therapeutic agent for breast cancer, and further research efforts should focus on elucidating the mechanisms in detail." (PMID 34572561, 2021). "More importantly, all the UFMylation system factors, including UBA5, UFC1, UFL1, UFM1, and UfSP2, were highly expressed in ERα-positive breast cancer cell lines and tissues." (PMID 37947621, 2023). "Moreover, the expression of the ASC1 mutant, an UFMylation defective form, or knockout of the UBA5 inhibited tumor growth, suggesting that the UFMylation of ASC1 is important for the transactivation of ERα and thus breast cancer development." (PMID 35884562, 2022). "Moreover, UfSP2 depletion exacerbated ERα-mediated tumor formation; however, the expression of an ASC1-UFMylation-defective mutant or the depletion of UBA5 inhibited tumor growth, suggesting that the UFMylation of ASC1 is important for the transactivation of ERα and thus breast cancer development." (PMID 37947621, 2023).
Epileptic encephalopathy (4 papers, 2017 to 2025). A condition in which epileptiform abnormalities are believed to contribute to the progressive disturbance in cerebral function. "The two reports describing the role of biallelic variants in UBA5 in early-onset epileptic encephalopathy classify p.Ala371Thr as a hypomorphic allele that contributes to a severe neurological phenotype only when in trans with a LoF in UBA5." (PMID 28965491, 2017). "We describe compound heterozygous mutations in the UBA5 gene in two sisters with early-onset epileptic encephalopathy." (PMID 28965491, 2017). "In September 2016, two reports describing the pathogenic role of UBA5 biallelic variants in early-onset epileptic encephalopathy were published." (PMID 28965491, 2017). "Pathogenic complex heterozygous genotypes were also detected in the UBA5 gene by sequencing and comparative analyzing the genomes of a pair of sisters with early-onset epileptic encephalopathy and their unaffected parents." (PMID 39757643, 2025). "Here, we describe compound heterozygous mutations in the recently identified epileptic encephalopathy gene, UBA5, in two sisters with early-onset epileptic encephalopathy." (PMID 28965491, 2017).
pancreatic cancer (4 papers, 2021 to 2025). "While another independent study showed that the covalent ligand DKM 2-93 can specifically binds the catalytic cysteine residue (Cys250) of UBA5, thereby inhibiting UFMylation and significantly reducing pancreatic cancer cell viability in vitro and in vivo." (PMID 41179291, 2025). "Another study also indicated that the selective inhibition of UBA5 can hinder the development of pancreatic cancer in vitro and in vivo." (PMID 34572561, 2021). "Moreover, studies have shown that inhibiting UBA5 activity can effectively reduce the tumorigenic potential of pancreatic cancer cells." (PMID 41179291, 2025). "Another group used chemoproteomic screening of covalent ligands and found that UBA5 might be a potential therapy target for pancreatic cancer." (PMID 39247188, 2024). "One group identified that UBA5 could be a target for pancreatic cancer via chemoproteomic screening of covalent ligands." (PMID 39247188, 2024). "For instance, chemoproteomic screening identified that UBA5 inhibited the development of pancreatic cancer in vivo and in vitro, which could be a novel strategy for treating pancreatic cancer." (PMID 35884562, 2022). "Thus, UBA5 may serve as a novel therapeutic target for pancreatic cancer." (PMID 41179291, 2025).
Ataxia (3 papers, 2016 to 2025). Ataxia refers to impaired coordination of voluntary muscle movement. "The finding of a UBA5 mutation in cerebellar ataxia suggests that impairment of the UFM1 pathway may contribute to the neurological phenotypes of ARCA." (PMID 26872069, 2016).
autosomal recessive spinocerebellar ataxia-24 (3 papers, 2020 to 2025). "Mutations in UBA5 that encode ubiquitin-like modifier-activating enzyme 5 (UBA5) are the cause of autosomal recessive spinocerebellar ataxia-24 (SCAR24); moreover, splicing regulator Rbfox2 is required for Purkinje cell function." (PMID 40141263, 2025). "Human UBA5 is associated with autosomal recessive spinocerebellar ataxia-24 (SCAR24) and EIEE." (PMID 32899411, 2020). "Mutations in the UBA5 gene have been identified as the underlying cause of DEE44 and spinocerebellar ataxia with autosomal recessive 24 (SCAR24), both of which are inherited in an autosomal recessive manner." (PMID 40217280, 2023).
developmental and epileptic encephalopathy, 44 (3 papers, 2021 to 2023). Any early infantile epileptic encephalopathy in which the cause of the disease is a mutation in the UBA5 gene. "In most reported cases, biallelic UBA5 variants cause developmental and epileptic encephalopathy 44 (DEE44, OMIM: #617132)." (PMID 38079206, 2023).
developmental and epileptic encephalopathy (2 papers, 2023 to 2026). An epilepsy associated with developmental impairment that may be due to either the underlying etiology or the superimposed epileptic activity, or both. "Developmental and epileptic encephalopathy (DEE) 44 is an autosomal recessive neurological disorder caused by mutations in the UBA5 gene." (PMID 40217280, 2023). "We report a case of developmental epileptic encephalopathy induced by a compound heterozygous variant of the UBA5 gene." (PMID 40217280, 2023).
Dystonia (2 papers, 2021 to 2022). An abnormally increased muscular tone that causes fixed abnormal postures. "Biallelic mutations of UBA5 cause severe, early-onset developmental disorders that manifest during early infancy as severe irritability, followed by dystonia and impaired development." (PMID 36543799, 2022).